RPL8 (ribosomal protein L8)
Description:
Component of the large ribosomal subunit. The ribosome is a large ribonucleoprotein complex responsible for the synthesis of proteins in the cell.
Synonyms: L8; uL2
Tractability: Small molecule: an approved drug acts on it; a structure with a bound ligand is known; a high-quality ligand is known. PROTAC: UniProt records ubiquitination sites on it; ubiquitination databases record sites on it; its protein half-life has been measured; a small molecule that binds it is known. Other modalities: a drug acting on it is in phase 2 or 3 trials.
Target class: Other cytosolic protein
Gene: Protein-coding gene on chromosome 8 (144,789,765 to 144,792,587, reverse strand). Ensembl gene ENSG00000161016.
Subcellular location: Cytoplasm
Subcellular location (Human Protein Atlas): Cytosol; Endoplasmic reticulum; Nucleoli
Pathways (Reactome):
Metabolism of proteins: Eukaryotic Translation Termination; Formation of a pool of free 40S subunits; GTP hydrolysis and joining of the 60S ribosomal subunit; L13a-mediated translational silencing of Ceruloplasmin expression; PELO:HBS1L and ABCE1 dissociate a ribosome on a non-stop mRNA; Peptide chain elongation; Protein hydroxylation; Ribosome Quality Control (RQC) complex extracts and degrades nascent peptide; SRP-dependent cotranslational protein targeting to membrane; ZNF598 and the Ribosome-associated Quality Trigger (RQT) complex dissociate a ribosome stalled on a no-go mRNA
Metabolism of RNA: Major pathway of rRNA processing in the nucleolus and cytosol; Nonsense Mediated Decay (NMD) enhanced by the Exon Junction Complex (EJC); Nonsense Mediated Decay (NMD) independent of the Exon Junction Complex (EJC)
Cellular responses to stimuli: Response of EIF2AK4 (GCN2) to amino acid deficiency
Developmental Biology: Regulation of expression of SLITs and ROBOs
Disease: Viral mRNA Translation
Metabolism: Selenocysteine synthesis
Gene Ontology:
Molecular function: protein binding; RNA binding; structural constituent of ribosome
Biological process: cytoplasmic translation; negative regulation of myoblast fusion; spermatogenesis; striated muscle contraction; translation
Cellular component: cytoplasm; cytosol; cytosolic large ribosomal subunit; cytosolic ribosome; endoplasmic reticulum; focal adhesion; membrane; nucleolus; postsynapse; postsynaptic density; nucleoplasm; large ribosomal subunit; ribosome; synapse
Genetic constraint (gnomAD): Loss-of-function variants: 0 observed, 21.75 expected, observed/expected ratio (o/e) 0, 90% interval 0 to 0.14. The upper end of that interval is the gene's LOEUF score, 0.14, which puts it in group 1 of 6, group 1 being the genes least tolerant of losing a copy. Missense variants: 248 observed, 368.3 expected, observed/expected ratio (o/e) 0.67, 90% interval 0.61 to 0.75. Synonymous variants: 182 observed, 148.7 expected, observed/expected ratio (o/e) 1.22, 90% interval 1.08 to 1.38.
Homologues: Orthologues: dog RPL8 (100% identical), macaque RPL8 (100% identical), mouse Rpl8 (100% identical), rat AC129049.1 (98% identical), tropical clawed frog rpl8 (98% identical), zebrafish rpl8 (97% identical), Drosophila melanogaster RpL8 (79% identical), Caenorhabditis elegans rpl-2 (74% identical). Paralogues in human: MRPL2 (22% identical).
Diseases named in the same sentence as RPL8 in open-access papers:
RPL8 is named in the same sentence as 43 diseases in open-access papers, as found by Europe PMC text mining. Sharing a sentence is not in itself a finding about the gene and the disease. The quoted sentences say what the papers report.
melanoma (5 papers, 2018 to 2024). A malignant, usually aggressive tumor composed of atypical, neoplastic melanocytes. "RPL8, a constitutive RP gene, is implicated in multiple tumor types, including liver cancer, melanoma, and ovarian cancer, while the mechanisms of RPL8 affecting related biological pathways in tumors are still unclear." (PMID 38155938, 2023). "RPL8 cannot only stimulate T helper (Th) cell cloning but also affect the proliferation of lymphocytes and the expression of cytokines in melanoma patients." (PMID 38155938, 2023). "Additionally, six cancer cohorts – prostate, breast, liver, lung, melanoma, and head and neck – contained tumor clusters distinguished by overexpression of RPL8, RPL30 and RPS20, with shared expression patterns of 19 other RPTs." (PMID 29530001, 2018). "Our results indicate that this amplification and the ensuing overexpression of RPL8 and RPL30 also occurs in subsets of melanoma, liver, prostate, lung, and head and neck cancers." (PMID 29530001, 2018).
glioma (4 papers, 2018 to 2022). A benign or malignant brain and spinal cord tumor that arises from glial cells (astrocytes, oligodendrocytes, ependymal cells). "Since RPL8 is part of the ribosomal 60S subunit and participates in protein synthesis, RPL8 antigen is considered to be a relevant vaccine target for glioma." (PMID 33635875, 2021). "Out of these 14 drugs, only four were found to have the anti-tumor effects in glioma therapy and targeted to RPL8 and PPSA genes." (PMID 33635875, 2021). "Considering the similarity of fetal and tumor at the differential state level, we speculate that in the diffuse astrocytoma, the expression level of RPL7 and RPL8 may be quite different from the other two glioma subtypes." (PMID 30322114, 2018). "RPL8, a component of the 60S subunit of ribosome, is involved in protein synthesis and RPL8 antigen may represent a relevant vaccine target for patients with glioma." (PMID 29687002, 2018). "Four drugs (Puromycin targeting RPL8; Doxorubicin, Daunorubicin, Mitoxantrone targeting RPSA) were identified as potential drug candidates with antineoplastic activities and played the vital role in Glioma therapy." (PMID 33635875, 2021).
osteosarcoma (4 papers, 2021 to 2023). A usually aggressive malignant bone-forming mesenchymal neoplasm, predominantly affecting adolescents and young adults. "RPL8 amplification was closely associated with osteosarcoma pathogenesis." (PMID 38155938, 2023). "RPL8 is reported to be involved in the occurrence of many diseases including osteosarcoma (OS) and also the corresponding treatment targets." (PMID 33635875, 2021). "RPL8 was dysregulated in osteosarcoma and hepatocellular carcinoma samples." (PMID 38155938, 2023).
bladder cancer (2 papers, 2016 to 2023). "Through PPI network analysis, we identified RPL8 and F2 as therapeutic drug targets that were significantly overexpressed in bladder cancer." (PMID 37147328, 2023). "This shows that RPL8 is associated with viral infection and its role in establishing NDV persistent infection in TCCSUP bladder cancer cell line is biologically significant in this study." (PMID 37147328, 2023).
glioblastoma (2 papers, 2022 to 2024). The most malignant astrocytic tumor (WHO grade IV). "RPL8 has been identified as one of the candidate proteins that are significantly associated with the prognosis of the most aggressive brain cancer-glioblastoma and temozolomide treatment." (PMID 36011399, 2022).
Hyperglycemia (2 papers, 2024 to 2025). An increased concentration of glucose in the blood. "In diabetic mother, ten Hub genes (RPL36, RPS29, RPL8 and so on) are key factors in the increased macrosomia in hyperglycemia." (PMID 38660519, 2024).
liver cancer (2 papers, 2022 to 2023). An epithelial or non-epithelial malignant neoplasm that arises from the liver. "More importantly, in the present study, the single-cell sequencing analysis results implied that SLC7A11, SLC1A5, CARS1, RPL8 and TFRC were not only upregulated in liver cancer cells but also expressed in immune cells." (PMID 35847985, 2022).
multiple sclerosis (2 papers, 2021 to 2025). A progressive autoimmune disorder affecting the central nervous system resulting in demyelination. "It has been reported that RPL8 was related to multiple sclerosis (MS) and was a potential biomarker of MS." (PMID 34926448, 2021).
ovarian carcinoma (2 papers, 2023). A malignant neoplasm originating from the surface ovarian epithelium. "Furthermore, in ovarian cancer, protein RPL8 is regarded as a specific tumor antigen." (PMID 38155938, 2023).
Cerebral ischemia (1 paper, 2021). Restriction of arterial blood supply to the brain associated with insufficient oxygenation to support the metabolic requirements of the tissue. "Moreover, the hub genes RPS9 and RPL8 of PPI network analysis were significantly increased in the brain tissue after cerebral ischemia and hemorrhage." (PMID 33613646, 2021).
cervical squamous cell carcinoma (1 paper, 2023). A squamous cell carcinoma arising from the cervical epithelium. "For the last step, the expression levels and prognostic values of RPL8 in cervical squamous cell carcinoma and endocervical adenocarcinoma (CESC) were examined from the TCGA database." (PMID 38155938, 2023).
cleft palate (1 paper, 2025). Cleft palate is a fissure type embryopathy that affects the soft and hard palate to varying degrees. "Other research has also suggested that RPL8 may be a potential key regulatory factor in the pathogenesis of cleft palate." (PMID 41010056, 2025).
colitis (1 paper, 2025). Inflammation of the colon. "In a DSS-induced colitis model, we observed that activation of the HMGB1/TLR4/NF-kB pathway resulted in decreased GPX4 expression, accompanied by increased mRNA levels of ferroptosis-related indicators (PTGS2, IREB2, CS, RPL8, and ATP5G3), which was further verified by cellular experiments." (PMID 40689397, 2025).
colorectal cancer (1 paper, 2025). A primary or metastatic malignant neoplasm that affects the colon or rectum. "Not only in colorectal cancer (COAD), but RPS7, RPL8 and RPL30 also have higher expression in tumour tissues in various tumours, such as Thymoma (THYM) and large B‐cell Lymphoma (DLBC)." (PMID 40770837, 2025).
Crohn disease (1 paper, 2025). A gastrointestinal disorder characterized by chronic inflammation involving all layers of the intestinal wall, noncaseating granulomas affecting the intestinal wall and regional lymph nodes, and transmural fibrosis. "By integrating multi-omics approaches, this study reveals a crucial connection between ferroptosis and immune microenvironment dysregulation in Crohn’s disease (CD), identifying seven hub ferroptosis-related differentially expressed genes (FEDGs): SCD, ATF4, SAT1, RPL8, MUC1, MTDH, and ATP6V1G2." (PMID 41515900, 2025).
depression (1 paper, 2025). "Although our analysis identified RPL8 as a potential key biomarker linking inflammatory bowel disease and depression, it should be acknowledged that the current biological evidence supporting this association remains limited." (PMID 41010056, 2025). "In this context, our findings highlight RPL8 as a candidate biomarker that may link inflammatory bowel disease and depression." (PMID 41010056, 2025). "Therefore, our findings provide novel evidence that RPL8 may serve as a shared biomarker and a promising therapeutic target bridging inflammatory bowel disease and depression, although further mechanistic investigations are clearly warranted." (PMID 41010056, 2025).
diffuse astrocytoma (1 paper, 2018). A low-grade (WHO grade II) astrocytic neoplasm. "Apart from XIST, the two homologues, namely, RPL7 and RPL8, have also been predicted to have quantitative patterns in diffuse astrocytoma." (PMID 30322114, 2018).
Disc Degeneration (1 paper, 2021). "Besides, RPL8 regulates the protein synthesis process of Disc Degeneration (DD), suggesting that COL3A1 might be used for the diagnosis and treatment of DD." (PMID 33635875, 2021).
endometriosis (1 paper, 2023). The growth of functional endometrial tissue in anatomic sites outside the uterine body. "GCH1, RPL8, PKLR, and MAOA were the key targets of paeonol in the treatment of endometriosis." (PMID 36677710, 2023).
hepatocellular carcinoma (1 paper, 2025). A malignant tumor that arises from hepatocytes. "Previous studies have shown that silencing RPL8 inhibits the progression of hepatocellular carcinoma by downregulating the mTORC1 signaling pathway." (PMID 41010056, 2025).
intracerebral hemorrhage (1 paper, 2022). A cerebrovascular disorder characterized by bleeding into one or both cerebral hemispheres including the basal ganglia and the cerebral cortex. "After intracerebral hemorrhage, human brain RPL8 mRNA expression increased, suggesting it may be a therapeutic target." (PMID 36438734, 2022).
leukemia (1 paper, 2024). A malignant (clonal) hematologic disorder, involving hematopoietic stem cells and characterized by the presence of primitive or atypical myeloid or lymphoid cells in the bone marrow and the blood. "Treatment of Cpd_DC60 also suppressed the expression of RPL8 and RPS2, resembling the impact caused by SGF29 depletion in leukemia." (PMID 38394203, 2024). "Last, CRISPR depletion of Rpl8 and Rps2 inhibited the MLL-AF9 cell survival, resembling the effect of sgSgf29 on these leukemia cells." (PMID 38394203, 2024). "Notably, ectopic expression of RPL8 and RPS2 was insufficient to reverse the impact triggered by sgSGF29, suggesting additional factors downstream of SGF29 are likely required for leukemia maintenance." (PMID 38394203, 2024).
pancreatic cancer (1 paper, 2021).
prostate carcinoma (1 paper, 2018). A carcinoma that arises from epithelial cells of the prostate gland. "In other cases, expression patterns appeared to be dominated by the differential relative expression of one or two RPTs, as seen with prostate cancer Cluster 2 and HCC Cluster 3, both of which possess tumors that overexpress RPL8 and under-express RPL3." (PMID 29530001, 2018).
psoriasis (1 paper, 2022). An autoimmune condition characterized by red, well-delineated plaques with silvery scales that are usually on the extensor surfaces and scalp. "Some important ferroptosis driver genes, such as RPL8, NCOA4, and ALOXE3, are expressed at low levels in the keratinocyte population in psoriasis." (PMID 35962439, 2022).
retinal degeneration (1 paper, 2023). Degeneration of the retina. "Values obtained for Kv1.3 channel RNA were normalized against the RNA levels of the housekeeping gene RPL8, which remains stable during retinal degeneration." (PMID 37762510, 2023).
tumor (19 papers, 2002 to 2025). "Tumour cells showed elevated stemness‐associated ribosomal genes (RPS7, RPL8, RPL30), which serve as diagnostic/prognostic biomarkers and therapeutic targets." (PMID 40770837, 2025). "In the TNF signalling communication network, we observed that high‐stemness tumour cells were less regulated by immune cells, suggesting a potential association between tumour cell stemness and immune evasion, consistent with poor RFS of RPS7, RPL8 and RPL30." (PMID 40770837, 2025). "Tumour cells with upregulated stemness‐related ribosomal proteins (RPS7/RPL30/RPL8) evade TNF‐mediated clearance." (PMID 40770837, 2025). "Concurrently, tumour cells elevate stemness‐associated ribosomal proteins (RPS7, RPL8, RPL30), enabling evasion of TNF signalling‐mediated surveillance." (PMID 40770837, 2025). "Meanwhile, TNFRSF18− T cells have exhibited stronger immunoregulatory activity through the TNF pathway, while tumour cells with high stemness characteristics (high expression of RPS7/RPL30/RPL8) were more resistant to TNF‐mediated immunoregulation." (PMID 40770837, 2025). "We found that RPL8 was able to regulate the AS of other genes and that many RASGs were enriched in tumor pathways." (PMID 38155938, 2023). "RPL8 as a ferroptosis driver, which encodes RPL8/uL2, a protein of the 60S large ribosomal subunit, has an overexpression in HCC tumor." (PMID 37461802, 2023). "RPL8, a ribosomal protein involved in protein synthesis, is significantly overexpressed in various types of tumor cells and is a predictor of clinical outcomes in patients with cancer." (PMID 34361002, 2021). "Moreover, we show that tumour cells displayed elevated expression of stemness‐associated ribosomal genes (RPS7, RPL8, RPL30), peaking at stage T4, which correlated with poor prognosis and immune escape." (PMID 40770837, 2025). "Although RPL8 is associated with many tumors, the specific biological functions of RPL8 affecting tumor occurrence and development remain unknown." (PMID 38155938, 2023). "RPL8 might affect the phenotypes of cancer cells by altering the transcriptome profiles, including gene expression and splicing, which provides novel insights into the biological functions of RPL8 in tumor development." (PMID 38155938, 2023). "We further examined the expression of RPS7, RPL8 and RPL30 in other tumours using the GEPIA database." (PMID 40770837, 2025). "Differential expression analysis of TCGA-LIHC tumor tissues and adjacent normal tissues revealed that the expression differences of TMEM45A, S100A10, SERPINA12, BHMT, CFHR3, RPL8, and STMN1 all exceed a 2-fold change." (PMID 39176099, 2024). "RPL8 showed a slightly higher expression level in tumor samples, and the overall survival outcome of CESC patients with higher RPL8 values was worse than that of the patients with lower RPL8 values." (PMID 38155938, 2023). "Also, the public scRNA‐seq data showed that RPS7, RPL8 and RPL30 in tumour cells were highly expressed relative to epithelial cells (Log2FC > 1)." (PMID 40770837, 2025).